CD69 (CD69 molecule)
Diseases named in the same sentence as CD69 in open-access papers (continued):
Sharing a sentence is not in itself a finding about the gene and the disease.
acute GVHD (1 paper, 2016). "We have also shown that a distinct relative decrease in CD69+ T-cells in a flow cytometry-based allogeneic MLC can be predictive of acute GVHD." (PMID 27965986, 2016). "Additionally, we could detect a significant correlation between a decrease in the frequency of CD69+ T-cells and incidence of acute GVHD grades II–IV even in this small material." (PMID 27965986, 2016). "Thus, low levels of CD69+ T-cells after MLC might serve as an indicator of increased alloreactivity and risk for incidence of acute GVHD." (PMID 27965986, 2016).
Acute hepatitis (1 paper, 2022). Acute hepatic injury resulting from inflammation typically accompanied by increased serum alanine transaminase activity. "In order to elucidate, whether this activation is iNKT cell specific or a general effect on lymphocytes due to increased inflammation during acute hepatitis, we compared the expression of CD38 and CD69 on iNKT cells, as well as on CD4+ and CD8+ T cells longitudinally in each individual patient." (PMID 34905514, 2022).
allergic conjunctivitis (1 paper, 2020). "Remarkably, when we stimulated PBMC in patients with perennial allergic conjunctivitis with Der p, we observed that TLR4 and CD69 were increased in CD4+T cells, suggesting that allergen-specific stimulation also induces TLR4." (PMID 33114004, 2020). "Remarkably, when we stimulated the PBMC of patients with perennial allergic conjunctivitis with Der p, we observed an increased TLR4 and CD69 in CD4+T cells, suggesting that allergen-specific stimulation also induces TLR4." (PMID 33114004, 2020).
asbestosis (1 paper, 2021). A lung disorder caused by inhalation of asbestos fibers. "CD28 expression was significantly decreased on CD8+ T cells in PB from patients with asbestosis, while CD69 and HLA-DR expression was significantly increased on CD8+ T cells in PB from these patients." (PMID 34022844, 2021).
astrocytoma (1 paper, 2023). "In contrast, the frequency of activated CD56+/CD69+ NK cells is significantly increased in patients with astrocytoma (** p < 0.01) and GBM (** p < 0.01) compared to the healthy controls (median frequencies of 3.1% (astrocytoma) and 2.5% (GBM) versus 0.9% (healthy donors))." (PMID 38137456, 2023).
atrial fibrillation (1 paper, 2022). A disorder characterized by an electrocardiographic finding of a supraventricular arrhythmia characterized by the replacement of consistent P waves by rapid oscillations or fibrillatory waves that vary in size, shape and timing and are accompanied by an irregular ventricular response. "The positive expression rates of CD69 and HLA-DR on peripheral blood CD3+ T lymphocytes were significantly higher in patients in the atrial fibrillation group than in the control group, and the differences were statistically significant (P < 0.01)." (PMID 35600045, 2022).
biliary atresia (1 paper, 2025). A rare, biliary tract disease characterized by progressive obliterative cholangiopathy of the intra- and extrahepatic bile ducts, occurring in the embryonic/ perinatal period, leading to severe and persistent neonatal jaundice and acholic stool. "We describe parallel increases involving pro-inflammatory CD16+ monocytes and CD103+CD69+CD8+ Trm cells in children with advanced biliary atresia." (PMID 40607400, 2025).
brain tumor (1 paper, 2023). "In our study, T-αFGL2, compared with T-Ctr, increased the population of CD69+CD8+ TRM-like cells in the brain tumor environment." (PMID 36759517, 2023).
breast adenocarcinoma (1 paper, 2022). "(d, e) Cells from (b) were co-cultured with HER2+ SKBR3 human breast adenocarcinoma cells for the indicated times and analyzed by flow cytometry for upregulation of activation marker CD69 (d) and GFP expression from the NF-κB reporter (e)." (PMID 35506657, 2022).
Burkitt lymphoma (1 paper, 2022). A rare form of malignant mature B-cell non-Hodgkin lymphoma. "As it was expected, anti-huCD20(hγ1)-IL2no-alpha increased NK cell activation upon co-incubation with human Burkitt’s lymphoma cells, as shown by the upregulation of CD69, the downregulation of CD16 and increased levels of CD107a." (PMID 36569901, 2022).
cancer-testis (1 paper, 2018). "We detected evidence of type I (interferon-γ producing), activated (CD69+) CD4+ and CD8+ antigen-specific T cell immunity against cancer-testis (NY-ESO-1) as well as melanocytic lineage (MART-1, gp100) antigens in the absence of therapeutic vaccination." (PMID 29973204, 2018).
Candida infection (1 paper, 2018). "In this pilot project, we describe the diagnostic potential of quantitating Candida-reactive, CD4/CD69/CD154 positive lymphocytes in blood of patients with invasive Candida infection." (PMID 29988394, 2018).
cardiotoxicity (1 paper, 2025). Toxicity that impairs or damages the heart. "CDR3 sequences associated with the CD8 CD69 + PD-1 + T cell subset (cluster 10), characterized by elevated GZMK expression, were also identified in the CD8 GZMK + subset of cardiotoxicity patients (cluster 3)." (PMID 41510228, 2025).
cerebral malaria (1 paper, 2015). A sequestration of Plasmodium falciparum in the brain, which can cause coma and/or seizures. "This was particularly marked for innate lymphocytes, NK cells, and γδ T cells (for each acute malaria group compared to control group, P < 0.001) and most evident in children with cerebral malaria (median values of CD69+ cells, 73% for NK cells and 60% for γδ T cells)." (PMID 26581890, 2015).
childhood asthma (1 paper, 2022). "Results showed that the mRNA expression levels of CD3D, CD3G, HLA-DMB, CD69, RGS1, and CIITA were significantly upregulated in childhood asthma patients compared with healthy controls, consistent with bioinformatics analysis." (PMID 36118895, 2022). "Based on qRT-PCR validation, CD3D, CD3G, HLA-DMB, CD69, RGS1, and CIITA were shown to be upregulated in childhood asthma patients." (PMID 36118895, 2022). "Results showed that the mRNA levels of CD3D, CD3G, HLA-DMB, CD69, RGS1, and CIITA were significantly upregulated in childhood asthma patients compared with the control individuals." (PMID 36118895, 2022).
Chronic colitis (1 paper, 2013). A chronic inflammatory disease of the large intestine (colon, cecum and rectum). "DSS-induced chronic colitis was dramatically attenuated in CD69 KO mice, as indicated by the reduced weight loss and disease activity index of weight loss, bleeding, and diarrhea." (PMID 23785429, 2013). "In this study, we used CD69-deficient (CD69 KO) mice to assess the role of CD69 in the pathogenesis of dextran sulphate sodium (DSS)-induced acute and chronic colitis." (PMID 23785429, 2013). "Thus, CD69+ CD4 T cells may be involved in the disease progression of chronic colitis or the recovery from acute colitis." (PMID 23785429, 2013). "In summary, our results indicate that the CD69 expressed on CD4 T cells plays a critical role in the development of DSS-induced acute and chronic colitis via the efficient migration of activated CD4 T cells into the colon." (PMID 23785429, 2013). "We herein investigated the role of CD69 using a DSS-induced acute and chronic colitis model." (PMID 23785429, 2013).
chronic hepatitis B (1 paper, 2017). "TRM can be recognized by CD69 and/or CD103 expression and may play a role in the pathology of chronic hepatitis B (CHB) and hepatitis C virus infection (CHC)." (PMID 28733665, 2017).
chronic rheumatic heart disease (1 paper, 2025). "Thus, the drug increased the levels of CD3+ cells and activated CD69 cells in bronchial asthma, and the levels of CD3+, CD4+ and CD8+ T-lymphocytes in chronic rheumatic heart disease." (PMID 41463008, 2025).
chronic rhinosinusitis (1 paper, 2021). Chronic form of sinusitis. "CD69 expression on peripheral blood eosinophils was higher in patients with ECRS than in patients with chronic rhinosinusitis (non-ECRS)." (PMID 34356851, 2021).
Cm (1 paper, 2018). "To further confirm the proliferation and activation of the TCR Vγ1+ and TCR Vγ4+ γδ T cells at an early stage of Cm infection, we examined the lung TCR Vγ1+ and TCR Vγ4+ γδ T cell percentage and CD69 expression by FACS." (PMID 29670466, 2018).
CNS lymphoma (1 paper, 2025). "Furthermore, 5% of the CSF samples, which were collected from a patient with primary CNS lymphoma on day 2 after the fifth glofitamab administration, showed an increase in the quantity of CD25 and CD69+ T cells." (PMID 40755773, 2025).
coccidioidal infection (1 paper, 2014). "This scenario may explain the situation of the employee from campus A who had protracted, probable, symptomatic coccidioidal infection and an atypical serologic pattern, but who had a negative test result on the second CD69 lymphocyte-activation assay." (PMID 25148473, 2014).
Cognitive impairment (1 paper, 2017). Abnormal cognition is characterized by deficits in thinking, reasoning, or remembering. "Multivariate logistic regression analysis, using as dependent variable MHE and as independent variables CD4+T cell subsets, showed that the percentages of CD4+CD28− population and of CD69+ cells over the same population were associated with cognitive impairment measured by PHES." (PMID 28751644, 2017).
cutaneous leishmaniasis (1 paper, 2014). Leishmaniasis affecting the skin. "Culture of PBMCs from cutaneous leishmaniasis patients with Leishmania antigens resulted in upregulation of the activation markers CD25 and CD69 as well as increased frequency of CD25hiCD127- cells among CD4 T cells." (PMID 24568275, 2014).
Dengue hemorrhagic fever (1 paper, 2018). A serious condition caused by Dengue virus infection. "In cases of dengue hemorrhagic fever in human children, increased numbers of CD69+ natural killer cells, CD4+ T cells, and CD8+ T cells have been observed." (PMID 29771921, 2018).
diarrhoea (1 paper, 2023). "The majority of the responding CD4+ T cells were CD69+IFN-γ−TNF-α− in both rotavirus-positive and rotavirus-negative children with diarrhoea at acute and convalescence phases." (PMID 37268634, 2023).
eosinophilic pneumonia (1 paper, 2022). An inflammatory lung disorder characterized by an increased number of eosinophils in the lungs. "CD69 was highly enriched in the HSC of the control sample and associated with eosinophilic pneumonia, and this protein may act to transmit signals in natural killer cells and platelets." (PMID 35865544, 2022).
esophageal squamous cell carcinoma (1 paper, 2026). Esophageal squamous cell carcinoma (ESCC) is a type of esophageal carcinoma (EC) that can affect any part of the esophagus, but is usually located in the upper or middle third. "In esophageal squamous cell carcinoma intratumoral tissues, CD49a + NK cells with high CD103 and CD69 expression were increased in the CD56bright NK cell subset." (PMID 41530841, 2026).
experimental autoimmune encephalomyelitis (1 paper, 2023). An autoimmune demyelinating disease of the central nervous system that is produced experimentally in animals by the injection of homogenized brain or spinal cord in Freund's adjuvant. "Other models such as experimental autoimmune encephalomyelitis (EAE) in mice have shown that in B1KO and B2KO animals or mice pretreated with B1R blocker (DALBK) and B2R antagonist (HOE-140), a decrease in the CD69 + T cell population occurs." (PMID 37464053, 2023).
follicular lymphoma (1 paper, 2021). Follicular lymphoma is a form of non-Hodgkin lymphoma characterized by a proliferation of B cells whose nodular structure of follicular architecture is preserved. "Resveratrol has been reported to increase CD69 expression by inhibiting expression of BCL-6 and subsequently induced apoptosis of transformed follicular lymphoma." (PMID 34633989, 2021).
fungal infection (1 paper, 2025). "In our model, we identified IFNγ (or) IL-17 secreting total CD4 + T cells and CD69 + activated CD4 + T cells that regulate fungal infection during C. auris reinfection." (PMID 40294061, 2025).
gastritis (1 paper, 2021). Inflammation of the stomach. "As expected, OX40+ MAIT cells from H. pylori gastritis patients were found to express high levels of CD69 and CD25, which are T cell activating markers." (PMID 33777009, 2021).
Hashimoto thyroiditis (1 paper, 2023). An autoimmune disorder caused by the production of autoantibodies against thyroid tissue. "Suppression of T cell responses could play a clinical role in the development and course of Hashimoto’s thyroiditis, even at the stage of full progression of the disease, because the thyroid tissue of HT patients is infiltrated by CD69+ and CD25+, with moderate numbers of Foxp3+ cells." (PMID 37371976, 2023).
heart transplant (1 paper, 2021). "Interestingly, the most appealing evidence indicating that the circulatory CD8+ CD69+ cells are a key factor in antigen-related tissue destruction was demonstrated by histological findings of a heart transplant rejection specimen." (PMID 34442004, 2021).
Hepatosplenomegaly (1 paper, 2022). Simultaneous enlargement of the liver and spleen. "In children with active VL, lower frequencies of circulating MAIT cells with increased levels of CD69 expression and higher proportions of TNF-producing cells were significantly associated with hepatosplenomegaly." (PMID 36189274, 2022). "Furthermore, VL patients presenting hepatosplenomegaly had severely reduced MAIT cell frequency and increased CD69 expression." (PMID 36189274, 2022).
hip fracture (1 paper, 2014). Traumatic or pathological injury to the hip in which the continuity of either the femoral head, femoral neck, intertrochanteric or subtrochanteric regions is broken. "Although we failed to report signs of monocyte activation in hip fracture patients with depressive symptoms, an increase in T cells expressing the activation markers CD69 and HLADR was seen in hip fracture patients with depressive symptoms." (PMID 25628751, 2014). "Additionally, activated CD69+ve (p = .005) and HLADR+ve (p < .001) CD8 T cells, were also higher in depressed hip fracture patients compared to healthy controls." (PMID 25628751, 2014).
Hyperglycemia (1 paper, 2025). An increased concentration of glucose in the blood. "Immunofluorescence studies showed that hyperglycemia increases CD69 expression, but a comparative decrease in diabetic tissues compared to control tissues is an interesting finding." (PMID 41465460, 2025). "The protein expression of CD36, CD69, and CD274 was increased with hyperglycemia compared to control cells as evidenced by increased fluorescence." (PMID 41465460, 2025). "Limitations of the study and future perspective: The study highlights the effects of hyperglycemia on the expression of CD36, CD69, CD274, and TLR-7 in rat tissues and rat fibroblasts." (PMID 41465460, 2025). "The effect of hyperglycemia on the expressions of CD36 and CD69 is supported by the significantly increased mRNA expression and protein expression of CD36 and CD69 in healed wounds in diabetic rats." (PMID 41465460, 2025). "This study aims to investigate the effects of hyperglycemia on the expression of various factors, including surface receptors CD36, Toll-like receptor (TLR)-7, programmed death-ligand 1 (PD-L1, also known as CD274), and CD69, in tissues from diabetic rats compared to control rats." (PMID 41465460, 2025). "However, the effects of hyperglycemia on the expression of mediators of inflammation and angiogenesis (CD36), immune regulation (TLR-7 and CD69), and inflammation/tissue repair (CD274) regarding wound healing are unknown." (PMID 41465460, 2025). "Hyperglycemia significantly increases the expression of CD36, CD69, and CD274 and increases TLR-7 expression but not significantly in diabetic tissues compared to control tissues." (PMID 41465460, 2025).
hypersensitivity pneumonitis (1 paper, 2025). Hypersensitivity pneumonitis (HP) is a pulmonary disease with symptoms of dyspnea and cough resulting from the inhalation of an antigen to which the subject has been previously sensitized. "In patients with fibrotic hypersensitivity pneumonitis, ozanimod alleviated CD3/CD28 induction of CD69, IL-4, and TNF in CD8, but not CD4 T cells." (PMID 40243992, 2025).
hypersensitivity reactions (1 paper, 2023). "Considering the fact that delayed hypersensitivity reactions usually start after 24 h, the timing of the CD69 marker is clinically satisfactory." (PMID 37686102, 2023).
Hypertension (1 paper, 2022). The presence of chronic increased pressure in the systemic arterial system. "The SARS-CoV-2-specific CD8+ T cell responses (CD69+ CD137+) were detected in 8 (38.1%) of 21 in CAD, 14 (38.9%) of 36 in hypertension, 16 (72.7%) of 22 in DM, 11 (61.1%) of 18 in CRD, 6 (66.7%) of 9 in cancer versus 34 (60.7%) of 56 in the health control." (PMID 36434092, 2022).
hyperthyroidism (1 paper, 2023). Overactivity of the thyroid gland resulting in overproduction of thyroid hormone and increased metabolic rate. "In the present study, during treatment, NK cell percentage, and especially CD69+CD56brightNK cells decreased in both groups of treatment, but more consistently in the intervention group, which exhibited a significantly greater and prompter recovery from hyperthyroidism." (PMID 37124743, 2023).
Hypocalcemia (1 paper, 2022). An abnormally decreased calcium concentration in the blood. "However, the GCs induced hypocalcemia in PWBC containing culture medium was not accompanied by the activation of CD8+ T cells based on their surface CD69 expression in vitro." (PMID 35757710, 2022).
hypothyroidism (1 paper, 2023). Abnormally low levels of thyroid hormone. "CD69 (CD69 molecule) and hypothyroidism: Levels of CD69+ regulatory lymphocytes are increased in autoimmune thyroid disorder patients." (PMID 36782330, 2023).
ileitis (1 paper, 2014). "To confirm that iIELs were activated in this TNFΔARE ileitis model, we stained iIELs for expression of the activation marker CD69." (PMID 25310588, 2014). "Furthermore, we show activation of TNFΔARE/WT small intestinal iIELs in ileitis, with significantly higher CD69 expression in TNFΔARE/WT mice as compared to littermate controls." (PMID 25310588, 2014).
Immunodeficiency (1 paper, 2025). Failure of the immune system to protect the body adequately from infection, due to the absence or insufficiency of some component process or substance. "Downregulated genes in CD69+ CD4+ T cells were involved in cell adhesion (PTPRC; -0.38log2FC), differentiation (CD44; -0.38log2FC), and immunodeficiency (IL7R; -0.42log2FC) pathways." (PMID 41208955, 2025).
infarction (1 paper, 2022). A localised pathological necrosis of tissue resulting from obstruction of the blood supply usually by a thrombus, an embolus, or vascular torsion. "Cd69-deficient mice had worse recoveries after infarction, as they were unable to reach the baseline weight 1 week after LAD ligation." (PMID 36066993, 2022). "We observed a specific mobilization of CD69+ Tregs in wild-type mice after infarction, with a 2.5-fold increase in peripheral blood in the first 24 hours, mimicking the peripheral response in patients with MI." (PMID 36066993, 2022). "The percentage of CD69+ Tregs increased in the circulation in patients with MI, as determined by an overall increase in CD69 expression on Tregs after infarction in most of the patients." (PMID 36066993, 2022). "We evaluated whether the observed inhibition of γδT cells by CD69+ Tregs after infarction was mediated by CD39." (PMID 36066993, 2022). "Mice lacking CD69 showed increased myocardial inflammation and dysfunction, leading to a rapid decrease in survival during the first week after infarction." (PMID 36066993, 2022).
injury (1 paper, 2012). Damage inflicted on the body as the direct or indirect result of an external force, with or without disruption of structural continuity. "The expression of CD69 and CD25 increased both in CD4+ and CD8+ populations reaching maximum levels three months after HI brain injury." (PMID 22567156, 2012).